M1AP (meiosis 1 associated protein)
Description:
Required for meiosis I progression during spermatogenesis.
Synonyms: C2orf65; SPATA37; D6Mm5e; SPGF48
Tractability: PROTAC: ubiquitination databases record sites on it.
Gene: Protein-coding gene on chromosome 2 (74,557,883 to 74,648,350, reverse strand). Ensembl gene ENSG00000159374.
Subcellular location: Cytoplasm
Subcellular location (Human Protein Atlas): Mitochondria; Nucleoli
Gene Ontology:
Molecular function: identical protein binding; protein binding
Biological process: spermatogenesis; chromatin organization; female gamete generation; homologous chromosome pairing at meiosis; male meiosis chromosome separation; meiotic DNA double-strand break formation; resolution of meiotic recombination intermediates; RNA processing; meiosis I
Cellular component: cytoplasm; membrane; recombination nodule
Genetic constraint (gnomAD): Loss-of-function variants: 38 observed, 54.07 expected, observed/expected ratio (o/e) 0.7, 90% interval 0.54 to 0.92. The upper end of that interval is the gene's LOEUF score, 0.92, which puts it in group 3 of 6, group 1 being the genes least tolerant of losing a copy. Missense variants: 543 observed, 673.7 expected, observed/expected ratio (o/e) 0.81, 90% interval 0.75 to 0.87. Synonymous variants: 250 observed, 263.86 expected, observed/expected ratio (o/e) 0.95, 90% interval 0.85 to 1.05.
Homologues: Orthologues: chimpanzee M1AP (99% identical), macaque M1AP (96% identical), dog M1AP (82% identical), rabbit M1AP (81% identical), guinea pig M1AP (79% identical), rat M1ap (72% identical), mouse M1ap (72% identical), zebrafish m1ap (39% identical), tropical clawed frog m1ap (31% identical).
Diseases named in the same sentence as M1AP in open-access papers:
M1AP is named in the same sentence as 16 diseases in open-access papers, as found by Europe PMC text mining. Sharing a sentence is not in itself a finding about the gene and the disease. The quoted sentences say what the papers report.
acute myeloid leukemia (2 papers, 2020 to 2021). Acute myeloid leukemia (AML) is a group of neoplasms arising from precursor cells committed to the myeloid cell-line differentiation. "A retroviral insertion mutagenesis study showed that M1AP synergized with Cbfb (core-binding factor)-MYH11 (myosin, heavy chain 11) translocation during the onset of acute myeloid leukemia." (PMID 34604049, 2021). "M1AP is highly expressed in several cancers, though, a positive correlation between M1AP and MYC was observed only in human acute myeloid leukemia." (PMID 32411526, 2020).
lung carcinoma (2 papers, 2021 to 2023). "SNPs identified in the CLPP and M1AP genes may be useful in risk prediction models for lung cancer." (PMID 34604049, 2021). "Moreover, expression deficiency of CACNA2D2, which encodes for a new subunit of the Ca2+-channel complex, has been postulated as a possible link in the pathogenesis of lung cancer, similar to M1AP." (PMID 36980682, 2023).
Azoospermia (1 paper, 2022). Absence of any measurable level of sperm,whereby spermatozoa cannot be observed even after centrifugation of the semen pellet. "Our aim in this study was to understand how non-obstructive azoospermia (NOA)-related missense variants previously reported in meiosis 1-associated protein (M1AP) gene affect the protein structure of M1AP." (PMID 35341049, 2022).
Cryptozoospermia (1 paper, 2022). A type of oligozoospermia in which spermatozoa can be detected in an ejaculate only after centrifugation and inspection of the pellet. "Furthermore, bi-allelic genetic variants on meiosis 1-associated protein (M1AP, MIM 619098) gene were recently associated with both of NOA and cryptozoospermia in different patients." (PMID 35341049, 2022).
male infertility (1 paper, 2025). The inability of the male to effect fertilization of an ovum after a specified period of unprotected intercourse. "To determine whether M1AP and ZZS proteins are involved in human male infertility by recombination failure, we screened for biallelic/hemizygous loss-of-function (LoF) variants in the human genes to select men with presumed protein deficiency (N = 24)." (PMID 40374915, 2025).
primary testicular failure (1 paper, 2024). "The M1AP gene (Meiosis 1-Associated Protein, OMIM: 619098) that is crucial for meiosis, and its dysfunction can lead to primary testicular failure, a major contributor to NOA." (PMID 38689732, 2024).
squamous cell carcinoma (1 paper, 2021). A carcinoma arising from squamous epithelial cells. "Notably, patients with rs10420388 and rs10418574 in CLPP showed a significantly increased risk of squamous cell carcinoma, while rs11126435 in M1AP was associated with decreased risk of adenocarcinoma." (PMID 34604049, 2021).
cancer (3 papers, 2020 to 2023). A tumor composed of atypical neoplastic, often pleomorphic cells that invade other tissues. "However, the role of M1AP in cancer progression remains unclear." (PMID 34604049, 2021).
adenocarcinoma (1 paper, 2021). A common cancer characterized by the presence of malignant glandular cells. "The variant allele T of SNP rs11126435 in the M1AP gene was associated with decreased risk of adenocarcinoma (OR = 0.95; P = 0.027)." (PMID 34604049, 2021).
M1AP also shares sentences with these, for which no sentence is quoted: Infertility (2 papers); cervical carcinoma (1); lung adenocarcinoma (1); non-small cell lung carcinoma (1); ovarian carcinoma (1); thyroid carcinoma (1); uterine carcinosarcoma (1).